SMC1B (structural maintenance of chromosomes 1B)
Description:
Meiosis-specific component of cohesin complex. Required for the maintenance of meiotic cohesion, but not, or only to a minor extent, for its establishment. Contributes to axial element (AE) formation and the organization of chromatin loops along the AE. Plays a key role in synapsis, recombination and chromosome movements. The cohesin complex is required for the cohesion of sister chromatids after DNA replication. The cohesin complex apparently forms a large proteinaceous ring within which sister chromatids can be trapped. At anaphase, the complex is cleaved and dissociates from chromatin, allowing sister chromatids to segregate. The meiosis-specific cohesin complex probably replaces mitosis specific cohesin complex when it dissociates from chromatin during prophase I (By similarity).
Synonyms: SMC1L2; bK268H5; SMC1BETA
Tractability: PROTAC: ubiquitination databases record sites on it.
Gene: Protein-coding gene on chromosome 22 (45,344,063 to 45,413,619, reverse strand). Ensembl gene ENSG00000077935.
Subcellular location: Nucleus; Chromosome; Chromosome, centromere
Subcellular location (Human Protein Atlas): Cytosol; Nucleoplasm
Pathways (Reactome):
Reproduction: Meiotic synapsis
Gene Ontology:
Molecular function: DNA binding; ATP binding; ATP hydrolysis activity
Biological process: establishment of meiotic sister chromatid cohesion; chromosome organization; sister chromatid cohesion
Cellular component: meiotic cohesin complex; nucleoplasm; chromosome; nucleus; chromosome, centromeric region; cohesin complex; condensed nuclear chromosome; lateral element; synaptonemal complex
Genetic constraint (gnomAD): Loss-of-function variants: 49 observed, 116.71 expected, observed/expected ratio (o/e) 0.42, 90% interval 0.33 to 0.53. The upper end of that interval is the gene's LOEUF score, 0.53, which puts it in group 2 of 6, group 1 being the genes least tolerant of losing a copy. Missense variants: 924 observed, 1,150.5 expected, observed/expected ratio (o/e) 0.8, 90% interval 0.76 to 0.85. Synonymous variants: 357 observed, 403.76 expected, observed/expected ratio (o/e) 0.88, 90% interval 0.81 to 0.96.
Homologues: Orthologues: chimpanzee SMC1B (99% identical), macaque SMC1B (94% identical), pig SMC1B (89% identical), dog SMC1B (88% identical), rabbit SMC1B (85% identical), guinea pig SMC1B (84% identical), rat Smc1b (84% identical), mouse Smc1b (83% identical), tropical clawed frog smc1b (60% identical), zebrafish smc1b (53% identical), Drosophila melanogaster SMC3 (17% identical), Caenorhabditis elegans smc-3 (16% identical), and 2 more. Paralogues in human: SMC1A (54% identical), SMC4 (23% identical), SMC3 (19% identical), SMC2 (19% identical), CKAP4 (9% identical), CCDC157 (9% identical), CCDC122 (4% identical).
Diseases named in the same sentence as SMC1B in open-access papers:
SMC1B is named in the same sentence as 17 diseases in open-access papers, as found by Europe PMC text mining. Sharing a sentence is not in itself a finding about the gene and the disease. The quoted sentences say what the papers report.
Infertility (3 papers, 2015 to 2021). "REC8- and SMC1β-null mutations are sterile because of meiotic failure, whereas Smc1βfl/fl;Gdf9-iCre female mice are fertile, in contrast to the infertility observed in our breeding trials." (PMID 34935904, 2021). "Deletion of meiosis-specific cohesin subunits in mice (Rec8−/−, Smc1b−/− and Rad21L−/−) showed defects in synapsis and infertility and premature reproductive senescence in Rad21L−/− females associated with a defect in primordial follicles." (PMID 26232174, 2016). "In contrast, in meiocytes where the levels of SMC1B are very high, the depletion of SMC1B results in infertility." (PMID 26673124, 2015).
aneuploidy (2 papers, 2025 to 2026). Chromosomal disorder consisting of the presence a chromosomal abnormality in which there is an addition or loss of chromosomes within a set. "Our analyses further revealed that a common haplotype spanning the meiotic cohesin SMC1B is associated significantly with both crossover count and maternal meiotic aneuploidy, with evidence supporting a non-coding cis-regulatory mechanism." (PMID 41565805, 2026). "Our analyses further revealed that a common haplotype spanning the meiotic cohesin SMC1B is significantly associated with both crossover count and maternal meiotic aneuploidy, with evidence supporting a non-coding cis-regulatory mechanism." (PMID 40321295, 2025).
bladder cancer (1 paper, 2022). "Other genes associating with this component were CHD3 in bladder cancer, HERC2 in ovary cancer, PIK3C2B in lung squamous cell cancer, EP300 in skin cancer (and breast cancer at a FDR of 2%), RBBP5 in pan-cancer, and SMC1B in pan-cancer." (PMID 35764656, 2022).
fertility disorders (1 paper, 2025). "The differential sensitivity of gonadogenesis to Smc1b loss between species and alleles warrants further investigation into potential Smc1b involvement in human fertility disorders affecting early ovary development." (PMID 40857739, 2025).
hepatocellular carcinoma (1 paper, 2023). A malignant tumor that arises from hepatocytes. "The overexpression of SMC1B was found to be associated with poor overall survival in hepatocellular carcinoma." (PMID 37655157, 2023).
lung adenocarcinoma (1 paper, 2023). A carcinoma that arises from the lung and is characterized by the presence of malignant glandular epithelial cells. "In conclusion, we identified GULPsig, consisting of IGF2BP1, IGF2BP3, SMC1B, CLDN6, and LY6K, as a potential prognostic signature for lung adenocarcinoma patients." (PMID 37655157, 2023).
metastatic prostate carcinoma (1 paper, 2022). A carcinoma that arises from the prostate gland and has spread to other anatomic sites. "It demonstrates a tightly associated sub-network of the meiotic cell cycle with strictly meiosis-specific (i.e., HORMAD1, MND1, SMC1B) genes and includes CT genes such as TTK and PBK (known also for metastatic prostate carcinoma)." (PMID 36499258, 2022).
Primary amenorrhea (1 paper, 2020). "One woman presenting primary amenorrhea had the p.Gln1177Leu heterozygous missense variant in SMC1B and the p.Ser5Arg heterozygous missense variant in the BMP15 gene." (PMID 33095795, 2020).
cancer (6 papers, 2012 to 2022). A tumor composed of atypical neoplastic, often pleomorphic cells that invade other tissues. "For example, in the cancer hallmark genome instability and mutation, the gene SMC1B and lncRNA MIR9‐3HG showed both strong co‐expression (PCC = 0.76) and co‐occurrence (P‐value = .008) of mutations in OSCC." (PMID 32202050, 2020). "Since we found that SMC1B silencing led to gene expression dysregulation, it is plausible cohesin-SMC1B deregulation by mutation or epimutation may provide a potential source of destabilizing changes for allowing the transformation of a normal somatic cell into a cancer cell." (PMID 26673124, 2015). "This indicates that the potential misregulation of somatic cohesin by STAG3 is a common event in cancers, while the expression of full meiotic cohesin, to include SMC1β and RAD21L, appears to be rare." (PMID 25408876, 2013). "COSMIC database of cancer genomic data contains 15 examples of mutations in RAD21L, some of them reoccurring, 83 mutations in SMC1β, and 88 in STAG3." (PMID 25408876, 2013). "It must be noted, however, that the baseline in gene expression experiments in somatic cancers may have been too high to detect a biologically meaningful activation of SMC1b and RAD21L." (PMID 25408876, 2013). "For example in a recently published dataset of only 33 cancer cell lines, six were shown to express RAD21L, with two co-expressing SMC1b with RAD21L." (PMID 25408876, 2013). "RAD21L, SMC1β and STAG3 subunits have drastically distinct patterns of activation/overexpression in cancers, however." (PMID 25408876, 2013).
tumor (5 papers, 2012 to 2022). "Univariate Cox regression analysis showed that STAG2, SMC1B, M stage, N stage, clinical stage, and residual tumor status were significantly associated with the OS of ESCA patients (P < 0.05)." (PMID 35371307, 2022). "A body of emerging evidence has revealed that meiotic chromosome regulator genes, including REC8, SMC1β, RAD21L1, TEX19, HORMAD1, and SYCP3, are inappropriately activated to modulate chromosome maintenance and segregation in tumor development, maintenance, and spread." (PMID 34150762, 2021). "In addition, consistent with previous research results, we also found that SMC1A, SMC1B, SMC2, SMC3, SMC4, and SMC6 were overexpressed at the mRNA level in HCC when compared with non-tumor cells." (PMID 34527684, 2021).
SMC1B also shares sentences with these, for which no sentence is quoted: breast carcinoma (1 paper); cervical cancer (1); Fanconi anemia (1); lung carcinoma (1); lung squamous cell cancer (1); ovary cancer (1); skin cancer (1).